MX1 (MX dynamin like GTPase 1)
Diseases named in the same sentence as MX1 in open-access papers (continued):
Sharing a sentence is not in itself a finding about the gene and the disease.
tumor (77 papers, 2009 to 2025). "Effects of cancer cell-extrinsic STAT3 deficiency on anti-tumor immunity have initially been reported in an inducible STAT3 knockout mouse model (Stat3fl/fl Mx1-Cre mice)." (PMID 35865518, 2022). "High expression of IFNβ1 in fibroblasts was weakly, but significantly, positively associated with high MX1 expression in the tumour cells (Spearman’s correlation r = 0.210; p = 0.028), suggesting that signalling between the cell types was active." (PMID 33398063, 2021). "High expression of IFNβ1 in fibroblasts, and MX1 in tumour cells were each significantly associated with poorer disease-free survival (by means of almost 800 days; p < 0.02 for both)." (PMID 33398063, 2021). "The results showed an association between MX1 expression and the clinicopathological features’ characteristic of aggressive behaviour, which strengthens the putative role of MX1 in tumour progression." (PMID 32350677, 2020). "High MX1 protein expression was associated with features of aggressiveness, including large tumour size, high tumour grade, high Nottingham prognostic index scores, hormone receptor negativity and high Ki67 expression." (PMID 32350677, 2020). "The inactivation of the clusterin gene (CLU), deleted in ~55% of TCGA cases, was associated with neoplastic transformation and tumor progression, while downregulation of MX1 was involved in proliferation, progression and metastasis of PC cells." (PMID 30925701, 2019). "In the COSMIC database, 122 tumor-related mutations were identified in the human Mx1 gene from whole-genome, whole-exome, and transcriptome sequencing data of human cancers." (PMID 26411585, 2015). "For instance, the MeC derived from the largest IC cluster is highly enriched in interferon response genes, such as ISG15, IFI6, LY6E, and MX1, indicating that the underlying interferon response is among the most common source of transcriptional variation shared across tumor samples and cohorts." (PMID 37149682, 2023). "High MX1 protein expression was significantly associated with a large tumour size (p = 0.011), high histological grade, poor NPI, hormonal receptor negativity (ER− and PR−) (all p < 0.0001), younger age at diagnosis (p = 0.047) and premenopausal status (p = 0.040)." (PMID 32350677, 2020). "In this context, mx1 has been described as part of a subset of IFN-stimulated genes expressed due to a chronic IFN-I stimulation with a beneficial role for the tumor." (PMID 40271486, 2025). "Nanostring gene expression analyses demonstrated that both ICIs increased the numbers of tumor-infiltrating lymphocytes (TILs), specifically cytotoxic cells (i.e. Mx1, anti-LAG-3 p < 0.01; anti-PD-L1 p < 0.0001 vs." (PMID 40674934, 2025). "We observed significant upregulation of the transcriptional levels of Ifnb1, Ifit1, Ifit2, Ifit3, Irf7, and Mx1 in irradiated 4T1 tumor tissues and irradiated CT26, H22, and GL261 carcinoma cells." (PMID 40470716, 2025). "In contrast, tumor-associated macrophage (TAM)-rich neighborhoods (C02) showed downregulation of IFN-α/β signaling genes (e.g., IFITM3, OAS1-3, MX1, ISG15), suggesting potential immunosuppression." (PMID 41138165, 2025). "A study conducted with BC cell lines and tissue samples identified tumor suppressors MX1 and TXNIP as targets of miR-204, suggesting that the functions of this miRNA are directed toward cell death suppression and proliferation stimulation." (PMID 39199587, 2024). "Tumor-reactive T cells in the Runx1Runx1t1/+; Mx1-Cre mouse model also exhibited reduced naïve score, high cytotoxic score, and high senescence score." (PMID 39243082, 2024). "In the case of BC, the tumor suppressors MX1 and TXNIP have been identified as direct targets of miR-204." (PMID 39199587, 2024). "In summary, the results obtained from Runx1Runx1t1/+; Mx1-Cre mouse validated the specific role of ADGRG1 in tumor-reactive T cells of AML." (PMID 39243082, 2024).
tumor (continued). "At necropsy, combination approaches inhibited MX1 ex vivo primary tumour volumes by 79.9% (P < 0.0001), 75.5% (P = 0.0001), 71.7% (P = 0.002), by the conc.T + C., seq.C→T, and seq.T→C strategies, respectively, in comparison to control." (PMID 36941406, 2023). "Nevertheless, by using the MX dynamin like GTPase 1 (Mx1)-cre mouse line to delete Shp2, we surprisingly unveiled a tumor-inhibiting effect of polyIC, the reagent used to induce Mx1-cre expression, independent of Shp2 deletion in hepatocytes and KCs." (PMID 36828281, 2023). "By contrast, the repression of tumor growth in Mx1-Cre;Ptpn2fl/fl mice in which PTPN2 was deleted throughout the hematopoietic compartment was accompanied by inflammation and overt morbidity." (PMID 37500611, 2023). "At 2 h p.i., the MX-1 tumor uptake was 0.42 ± 0.11 %ID/g, which was remarkably lower than that in the BxPC3 tumor model (p < 0.001)." (PMID 36145541, 2022). "High expression of IFNβ1 (CAFs) or MX1 (tumour cells) correlated with reduced survival after chemotherapy, especially in claudin-low tumours (which MDA-MB-231 and MDA-MB-157 cells represent)." (PMID 33398063, 2021). "We constructed tissue microarrays containing triplicate cores of cancer tissue and assessed expression of IFNβ1 in fibroblasts and MX1 as a marker of active IFN signalling in tumour cells using immunohistochemistry." (PMID 33398063, 2021). "Genes ASPH, HSPB1, SQSTM1, ANXA2, and GSN (Cluster A) and PURA and MX1 (Cluster B) were downregulated for both datasets in PCa tissue vs. normal gland or normal adjacent to tumor tissue." (PMID 32640729, 2020). "An in vitro study conducted in colorectal carcinoma indicated that knockdown of MX1 in colon cancer cells inhibits migration and invasion of tumour cells." (PMID 32350677, 2020). "Overexpression of MX1 in BC has been reported previously in certain IHC subtype, highlighting its correlation with immune response and tumour infiltrating lymphocytes, TILs and it has been associated with anthracycline-based chemotherapy response." (PMID 32350677, 2020). "Apart from its role as a prominent antiviral protein in innate immunity, studies have indicated a role for Mx1 as a potential tumor suppressor gene." (PMID 32967656, 2020). "Overexpression of IFNAR1, MX1 and signal transducer and activator of transcription 1 (Stat1) indicated the endogenous IFNα activation in tumour microenvironment, which correlated with immunosuppression status in HNSCC patients." (PMID 30555157, 2019). "Together, although overexpression of IFNAR1 correlated with worse prognosis of HNSCC, activation of IFNα signalling was also evident as manifested by MX1 expression in tumour microenvironment of HNSCC." (PMID 30555157, 2019). "A recent study has reported an increase in tumor cell sensitivity to VSV induced by downregulation of the MX1 gene." (PMID 30186768, 2018). "Pathological analysis of non-tumor portions showed a marked infiltration of immune cells in Mx1-Cre;Gankyrinf/f mice as compared with Gankyrinf/f mice." (PMID 28160571, 2017). "Gankyrin expression was much lower both in myeloid and epithelial cells of non-tumor colonic tissue of Mx1-Cre;Gankyrinf/f mice as compared with Gankyrinf/f controls." (PMID 28160571, 2017). "MX1 is an interferon-inducible GTPase, and it has been known to inhibit tumor cell motility and invasion." (PMID 27121770, 2016). "We also measured the cytoplasmic expression of Mx1 protein by flow cytometry in tumor cell lines and healthy primary cells." (PMID 26539644, 2015). "More strikingly, when we analyzed the expression of the ISG Mx1, we found this protein in the cytoplasm of all insensitive tumor cell lines and healthy cells exposed to MV." (PMID 26539644, 2015). "In contrast, eleven out of fifteen sensitive tumor cell lines were unable to express a high level of Mx1 in response to MV." (PMID 26539644, 2015).
tumor (continued). "Control MX-1 tumors grew by 907.4% (±37.4%) of the initial tumor volume by week five, but those treated with MIA-602 increased by 434.8% (±12.9%); significantly (P < 0.001) less than controls." (PMID 25593995, 2014). "MX1 was also predicted to have an inhibitory effect on tumor cell motility and invasion, an essential attribute for metastatic behavior." (PMID 22078224, 2011). "While some studies suggest that it promotes cell death by regulating genes like FOXA1, Bcl-2, JAK2, and PTEN, others indicate that it might suppress cell death by targeting tumor suppressors like MX1 and TXNIP and influencing ERα signaling." (PMID 39199587, 2024). "Many downregulated genes in tumour‐infiltrating peripheral CD8+ T cells are associated with classical IFN responses (IFI6, IFI27, MX1, STAT1, EPSTI1 PARP9, ISG15), cell proliferation (STMN1, CENPF, HELLS, NUSAP1, and DNPH1), and T cell costimulation (CD28, TMIGD2, TNFRSF4, CD27, and TNFRSF18)." (PMID 39350478, 2024). "Finally, the detection of mx1 within the neoplasm pinpoints to a yet undisclosed role of anti-cellular signaling in tumor immunity." (PMID 38962703, 2024). "Interestingly, in AA/Black samples, in addition to the tumor cells, MX1 staining was observed in tumor microenvironment cells, mostly Kupffer cells, indicating potential involvement of MX1 in regulating Kupffer cell function, hence inflammation." (PMID 37686559, 2023). "Similarly, correlations between survival and expression of each of IFNβ1 in fibroblasts and MX1 in tumour cells were maintained in claudin-low cases (p < 0.05) but lost in claudin-highs." (PMID 33398063, 2021). "In the ulcerated tumor, B cells showed increased markers associated with type-2 responses such as CCL17, IL4R, and decreases in interferon-stimulated genes (IFI44L, STAT1, IFITM1, MX1, IRF1)." (PMID 34583709, 2021). "Indeed, in B16 tumor-bearing mice, mProIFNa4-Fc induced a much lower level of an interferon-stimulated gene (ISG) MX1 than unmasked mIFNa4-Fc, while both induced similar MX1 expression levels in B16 tumor tissues." (PMID 34620867, 2021). "A study revealed that in HER2-positive BCs, MX1 is only expressed in the cytoplasm of tumour cells." (PMID 32350677, 2020). "Tumor suppressors, MX1 and TXNIP, were proven to be direct targets of the miRs." (PMID 27121770, 2016). "Metronomic CPA treatment also induced a core set of death-related genes that may be important for innate and/or adaptive immune activation by damaged tumor cells, including Sp110, Mx1, Mx2, Ebi3, Eomes, Tnfsf4, Gdf15, Ddx58, and Dhx58." (PMID 25952672, 2015). "Additionally, we found ADGRG1 could serve as the specific marker of CD8+ T tumor-reactive T cell and validated it through the Runx1Runx1t1/+; Mx1-Cre mouse model." (PMID 39243082, 2024). "For instance, IFIT1, IFIT3, IFI-16, ISG15, MX1, and OAS1 have been shown to have tumor-suppressive function." (PMID 40563638, 2025). "For instance, indicators associated with the IFN pathway, such as the characteristics of interferon-stimulated genes (ISGs) including MX1, EPSTI1, XAF1, and GBP1, have been correlated with tumor sensitivity to VSV." (PMID 40698086, 2025). "The epithelial activation markers REG and SERPINA5, the interferon response marker MX1, and the anti-inflammatory protein IL1RN were found significantly deregulated in tumour tissue, similar to the inflamed tissue." (PMID 36961872, 2023). "In the MX1 and MDAMB231 xenografts, statistically significant differences in in vivo normalised tumour volumes were observed with different treatments from day 8 and day 13 until necropsy, respectively, while only trends were observed with HCC1806." (PMID 36941406, 2023). "We selected four ISGs, OAS1, ISG15, MX1 and IFI6, for further validation by Taqman Q-RT-PCR in the HCC tumor tissues." (PMID 37686559, 2023).
tumor (continued). "Analysis of total tumor RNA extracted after 2, 4, and 7 CPA cycles revealed that the ISGs Cxcl10 and Mx1 were initially upregulated but returned to baseline after discontinuation of CPA treatment." (PMID 36187936, 2022). "The expression of representative ISGs including MX1, OAS3, and IFIT1 was found to be significantly higher in tumor cells compared to stroma cells." (PMID 34400640, 2021). "Using the TCGA-PRAD database, we observed a positive correlation in the expression profiles of MX1 and HMOX1, both in normal adjacent to tumor (Pearson = 0.3718; p = 0.0066) and in tumor tissue samples (Pearson = 0.4681; p < 0.0001)." (PMID 32640729, 2020). "Meanwhile, Abx treatment inhibited the expression of type I interferon (IFNβ), and ISGs (MX1, ISG15, and IFIT1) in small intestine and tumor tissues, validating its regulation on IRF3 activation." (PMID 33188184, 2020). "The results evidenced a significant positive correlation between MX1 and HMOX1 expression profiles, both in human tumor and normal adjacent to tumor tissue samples." (PMID 32640729, 2020). "Conversely, restoring IFN-β expression in OSM-expressing TNBC cells restored the expression of select ISGs (including STAT1, STAT2, IRF9, SOCS1, MX1, and OAS1 and reduced tumor sphere formation and tumor-initiating capacity." (PMID 31036052, 2019). "The results obtained significantly expand knowledge on the anti-cancer effect of furanocoumarins and their effect on the induction of apoptosis in derived tumor cell lines from the human hematopoietic system: HL60, HL60/MX1 and HL60/MX2." (PMID 31083598, 2019). "In Mx1-Cre;Gankyrinf/f mice, STAT3 activity was decreased in inflammatory cells whilst ERK activity was decreased in tumor cells as well as inflammatory cells." (PMID 28160571, 2017). "This suggests that in sensitive tumor cell lines that produce type I IFN and express Mx1 in response to MV, other ISG involved in the inhibition of MV replication are missing." (PMID 26539644, 2015). "As expected, the expression levels of STAT1 and MX1 were up-regulated in OSCC tumors (7/9 and 9/9 for STAT1 and MX1, respectively), whereas the levels of ANXA2 were similar between the tumor tissues and the adjacent normal tissues." (PMID 26110569, 2015). "Among the STAT1 targets investigated in our study, MX1 and CXCL10 can be considered as genes influencing tumor progression, since their expression was significantly associated with bad patient‘s prognosis." (PMID 24725474, 2014). "We observed that the combination therapy effectively circumvented the intrinsic resistance mechanisms and demonstrated potent anti-tumor activity in tumor models that did not respond to TOPO II inhibitor treatment alone (MX-1 and CTG-1017)." (PMID 38791158, 2024). "The constitutive presence of mx1 (transcripts and protein) in neoplastic cells was an unexpected finding as it has not been described in the context of canine neoplasia before." (PMID 38962703, 2024). "In the tumour cells, when present, MX1 was expressed in the cytoplasm with no discernible membranous or nuclear staining observed." (PMID 32350677, 2020). "In addition, we identified two novel target genes of miR-204/211, MX1 and TXNIP, which are tumor suppressors." (PMID 27121770, 2016). "In all insensitive tumor cell lines, we found cytoplasmic Mx1 in non-infected cells that was increased in the presence of MV, except for Meso52 where Mx1 was already present in equally high amounts in absence of the virus." (PMID 26539644, 2015). "On the contrary, tumor cell lines that are unable to develop a type I IFN response are sensitive to MV infection, with the four exceptions, Meso36, 37, 34 and 122, which express IFNA1, IFNB1 and MX1 and are sensitive to MV replication." (PMID 26539644, 2015). "Pattern 3 (‘attenuation’) on the other hand, consists of two known tumor inhibitors – NMI and MX1." (PMID 23630584, 2013). "The expression of mx1 is a novel finding not previously reported in canine neoplasia." (PMID 38962703, 2024).
tumor (continued). "Macrophage in this cluster had high expression of type I interferon signaling related genes (IFITM3, IFI27, MX1, IFI6, and ISG15) as well as gene features related to immunosuppressive phenotype (APOE, APOC1, S100A9, and GPNMB), whereby participating in tumor immune regulation." (PMID 35265520, 2022). "We also carried out multivariate analyses to assess whether IFNβ1 in fibroblasts and MX1 in tumour cells provided prognostic insights that were independent of the standard prognostic factors, lymph node status and tumour grade." (PMID 33398063, 2021). "In addition, exposure to IFN-α and IFN-β induced a strong expression of Mx1 in all of these fifteen sensitive tumor cell lines (data not shown)." (PMID 26539644, 2015). "In addition a set of 15 proteins that participate in the antitumor immune response such as the tumor suppressors PSMB9, ERAP1 and TAP1 or the interferon-stimulated genes IFIT1 and MX1 were found down-regulated in CUL4A-overexpresing cells and up-regulated in CUL4A-silencing models." (PMID 24870930, 2014). "MX1 is described to exert an antiviral activity by binding to cellular RNA helicases required for viral replication but was not ascribed any obvious function in tumor biology." (PMID 24725474, 2014). "Likewise, interferon response genes (including TLR3, MX1, RSAD2, IFI44, IFI27, IFIT1, and IFIT3), and chemokine genes (including CCL7, CXCL10, CXCR1, and CCL25) were significantly increased in PM-treated MM tumor tissues, whereas panobinostat showed minimal effects at equivalent doses." (PMID 40562746, 2025). "However, we ruled out this hypothesis since we observed only one Mx1-positive population in these tumor cell lines in the presence of MV." (PMID 26539644, 2015). "Both Stat3fl/fl Mx1-Cre and Stat3fl/fl Ncr1-iCre mice demonstrated that lack of STAT3 enhances NK cell-mediated surveillance in different transplantable tumor models." (PMID 35865518, 2022). "Our analyses showed that both tumor and nontumor cells expressed IFN signaling genes such as STAT1, STAT2, ISG15, OAS1, and MX1 in all three datasets." (PMID 34771447, 2021). "A number of interferon-stimulated genes (ISGs) were found to be highly induced in tumor compared to non-tumor samples, such as GBP1, CAMP, PTGS2, GOLIM4, IFIT3, MX1, LTF, and CYBB." (PMID 34400640, 2021). "In multivariate Cox regression analysis, high MX1 protein expression was an independent predictor of shorter BCSS (p = 0.028; HR = 1.5; 95% CI = 1.0–2.2) regardless of tumour grade, nodal stage, tumour size, HER2 status and basal phenotype." (PMID 32350677, 2020).